CXCR4 (C-X-C motif chemokine receptor 4)
Diseases named in the same sentence as CXCR4 in open-access papers (continued):
Sharing a sentence is not in itself a finding about the gene and the disease.
tumor (continued). "CXCL12, the sole chemokine ligand for CXCR4, was abundant in 6 out of 12 supernatants from the GNS cell cultures, however it was undetectable in all dissociated tumour biopsy and CUSA samples analysed." (PMID 35464424, 2022). "In the context of targeting CAFs in relation to the hypoxic tumor microenvironment, TGF-β, HIF, and CXCL12/CXCR4 signaling pathways are perhaps the most promising targets." (PMID 35884382, 2022). "CXCR4-directed imaging was less sensitive compared to FDG, and 68Ga-Pentixafor visualized tumour lesions in 10/11 patients, while 18F-FDG revealed sites of disease in all 11 patients." (PMID 36140541, 2022). "Next, we ascertained that metformin prevents a motile phenotype of BCAHC-1 cells triggered by the paracrine liaison between tumor cells and CAFs upon insulin activated CXCL12/CXCR4 axis." (PMID 35672854, 2022). "Expression profiles of MIF, CXCL12, and the receptors CXCR4, CXCR2, CXCR7, CD74, and CD44 were first analyzed using an RNA sequencing (RNA-seq) dataset (GSE62564) of 498 primary NB tumor samples." (PMID 35715791, 2022). "A recent study based on flow cytometry found that an increase in tumor-infiltrating plasmocytoid cells promotes OSCC proliferation, primarily by TNF-α/NF-κB/CXCR-4 pathway." (PMID 35634436, 2022). "In 2013, Feig and colleagues theorized that fibroblast cells in the tumor microenvironment (TME) produced the C-X-C motif chemokine 12 (CXCL12), the ligand of CXCR4, which antagonizes and blocks the immune response from killing PDAC cells." (PMID 35797269, 2022). "Tumor cell-macrophage hybrids express both macrophage (CD14, CD68, CD163, CD204, and CD206) and tumor-specific markers (ALCAM, MLANA, KRT, EpCAM, CXCR4, and CD44)." (PMID 35242760, 2022). "To test our conjecture, by further analysis, we found that CXCR4, a specific receptor for CXCL12, was expressed in T cells and macrophages in tumor tissues." (PMID 36211359, 2022). "As revealed by WB analyses, the expression of CXCL12, CXCR4, CCL21, and CCR7 proteins in SK-Hep1 cells was significantly increased after transfection with tumor-derived DNA in contrast to the blank control group." (PMID 35860597, 2022). "The CXCL12 ligand and its receptors CXCR4 and CXCR7 constitute an axis, which is involved in tumor progression." (PMID 35408440, 2022). "We evaluated the biodistribution of the T22-GFP-H6 nanocarrier in the CXCR4+ AN3CA subcutaneous model, measuring its uptake in tumor tissue and in non-tumor organs." (PMID 35884987, 2022). "CXCR4/CXCL12 signaling also activates the Hh pathway in other cancer types, thus increasing tumor size, cell motility, angiogenesis, EMT, cell invasion, and NANOG expression." (PMID 36118530, 2022). "CXCL12/CXCR4 signaling promotes an immunosuppressive environment, ECM remodeling, reprogramming of tumor cells, tumor angiogenesis, and metastasis." (PMID 35155581, 2022). "g, CCL1, CCL5, CCL7, CXCL8, and CXCL12) drive the recruitment of MDSCs to OC tumor sites via the CCR2, CXCR4, and CCR5 axes." (PMID 36532066, 2022). "Our findings suggested that the tumor-promoting interaction between the BM microenvironment and NB cells is mediated, in part, by the MIF/CXCR4 signaling axis." (PMID 35715791, 2022). "Similar to CXCR4 inhibitors, NOX-A12 increased tumor infiltration of T and NK cells and potentiated the activity of anti-PD-1 therapy in pre-clinical models." (PMID 36077755, 2022). "Investigating a potential interaction of CXCR4/CXCL12 axis with the AR, the most common therapeutic target for systemic therapies, IHC revealed AR expression in EC more affecting tumor areas compared to stromal tissue." (PMID 35717322, 2022). "CXCR4 and its ligand chemokine stromal derived factor‐1 (SDF‐1) play crucial roles in the recruitment of pDCs from peripheral blood to tumor and surrounding tissues." (PMID 34964283, 2022). "Acid sinomenine interferes with tumor-derived DNA and affects ERK/MMP signaling via the CXCL12/CXCR4 axis in HCC cells." (PMID 35860597, 2022).
tumor (continued). "Thus, our goal is to tackle the urgent need to develop therapeutic agents that could be exploited to achieve targeted delivery of bacterial exotoxins to CXCR4+ tumor cells and thus reach personalized therapy that enhances the antineoplastic effect while reducing adverse effects in EC patients." (PMID 36612081, 2022). "Studies have shown that upon agonist activation of CXCR4 and CB2 simultaneously, the functions of the malignant tumour cells were reduced." (PMID 35909575, 2022). "Mast cells, which can be both tumor-suppressing and tumor-promoting, can be recruited by CAFs via CXCL12 in a CXCR4-dependent manner." (PMID 36010899, 2022). "CXCR4 is highly expressed in PDA and is also expressed by T cells, leading to their immobilization within tumor sites via CXCR4 binding to the stromal derived factor-1 (SDF-1) or else known as CXCL12." (PMID 35466279, 2022). "The second MC group specifying perilesional skin gathered CD206lowCD204+ CXCR4+ cells (orange cells from MC36, MC43 and MC44) that resemble perivascular macrophages identified in tumor periphery." (PMID 36325333, 2022). "CXCR4 and CXCL12 are key to tumor cell migration and directly affect the formation of pre-metastatic niche." (PMID 35965504, 2022). "In HCC, overexpression of EZH2 represses miR-622 through H3K27me3 deposition and results in CXCR4 upregulation and unfavorable prognosis, while BMI1 enhances TGFβ2/SMAD pathway and facilitates tumor cell proliferation and cell cycle progression." (PMID 36566204, 2022). "Hypoxia is the main driver of EPCs homing at the tumor site—this induces, via HIF-1α expression, numerous growth factors, cytokines, and chemokines, including VEGF-A, CXCL12, and CXCR4." (PMID 35203510, 2022). "Among them, immune-related genes such as CCL2, CCR2, CXCR4, and CCR5 play a role in the recruitment of TAMs in tumor development and progression." (PMID 35874816, 2022). "Nevertheless, radiotracers with highest promises are probably the CXCR4 and FAP inhibitor ligands, targeting a tumor microenvironment." (PMID 35223907, 2022). "CXCR4 and its ligand, CXC chemokine ligand 12 (CXCL12), have been shown to be key regulators of tumor invasion and metastasis." (PMID 36103228, 2022). "CXCR4 and its chemokine ligand 12 (CXCL12), also known as the stromal cell-derived factor-1 (SDF-1), are two key factors in the cross-talking between tumor cells and their microenvironment." (PMID 35877436, 2022). "The results showed that MHC molecules, MIF-CD74/CXCR4, and MIF-CD74/CD44 in HSIL and lymph nodes were higher than those in tumor tissue." (PMID 35812401, 2022). "CXCL12, another chemokine secreted by osteoblasts, triggers DTC dormancy in the bone marrow by binding to C-X-C motif chemokine receptor 4 (CXCR4), one of the receptors of CXCL12 in tumour cells." (PMID 36307871, 2022). "Administering a CXCR4 antagonist to PDAC-bearing mice results in the rapid accumulation of CTLs, the arrest of tumour growth, and increased tumour sensitivity to the anti-PD-L1 antibody." (PMID 36284271, 2022). "For example, TNF-α, IL-6, IL-8, and IL-23 mediate inflammation resulting in tumor growth, and TGF-β and CXCL12/CXCR4 mainly promote metastasis." (PMID 36237303, 2022). "A study demonstrated that IFN-γ downregulates the expression of CXCR4 in HNSCC cell lines and consequently inhibits tumor cell migration and proliferation." (PMID 36376825, 2022). "Small molecules (chemokines), particularly CXCR4 and its ligand CXCL12, are overexpressed in the tumour microenvironment of most malignant tumours." (PMID 36140541, 2022). "For example, antagonists to CXCR4, CCR2, CCR5, and CXCR1/2 were developed to disrupt tumor invasiveness, but now have been observed to influence immune cell migration in the TME." (PMID 33603130, 2022). "Fast tumor growth generates hypoxia, which promotes the release of SDF-1 from platelets and the subsequent recruitment of CXCR4+/VEGFR+ cells (hemangiocytes) from the BM." (PMID 36393850, 2022).
tumor (continued). "CXCR4, a hypoxia-inducible chemokine receptor, interacts with CXCL12 to suppress CD8-positive cytotoxic T cells, thereby supporting immune evasion of tumor cells." (PMID 35884382, 2022). "The combination of CXCL12 and CXCR4 can activate signaling pathways such as MAPK/ERK, PI3K/Akt/NF-κB, and c-Jun N-terminal kinase and regulate tumor progression." (PMID 35647303, 2022). "Experiments using tumor samples derived from the tumor xenograft mouse models demonstrated that the expression of CBFB, OPN, Runx2, and CXCR4 proteins was significantly suppressed in CBFB-knockdown mice, compared with the control mice." (PMID 35903297, 2022). "Inhibition of CXCR4 and CXCR7 activity in vitro, reduction of tumor growth in vivo, release of plasma cells into circulation in vivo." (PMID 36358889, 2022). "The chemokine receptor system plays a relevant role in BC, where some chemokines and their cognate receptors, namely CXCL12 and its receptors CXCR4 and ACKR3 are found overexpressed and often dysregulated in both tumor and tumor microenvironment (TME) cells." (PMID 36233192, 2022). "CXCR4 is a seven transmembrane G protein-coupled receptor for CXCL12 (also called SDF-1) and a central receptor in tumor biology, and its expression controls proliferation and tumor cell survival in various tumor types." (PMID 35941537, 2022). "Following the co-internalization of CXCR4 and CD47 in tumor cells, macrophages phagocytose them and cross-present their antigens to the adaptive immune system, leading to tumor rejection in a fraction of mice." (PMID 35565443, 2022). "Increased proliferative capacity as well as expression of important factors for tumor growth and angiogenesis including Bcl-2, phosphorylated proteins ERK1/2, CXCR4, VEGF, and MDM2 mRNA was seen in those implanting with both MSC-EXOs and tumor cells." (PMID 36117723, 2022). "After in vitro evaluation of the CXCR4-targeted T22-GFP-H6 nanocarrier, subcutaneous EC models were used to study its uptake in tumor and normal organs." (PMID 35884987, 2022). "The receptor CXCR4 together with one of its chemokines, CXCL12 (also known as SDF-1), have been shown to play a key role in the tumor-stromal communication affecting cancer growth, angiogenesis and metastasis formation." (PMID 35397601, 2022). "Specifically, CXCL12 controls tumor progression by binding to its receptors, CXCR4 and/or CXCR7, and subsequently affecting tumor cell survival, proliferation, and migration." (PMID 36539774, 2022). "TGF-β/SMAD mediates the exosomal secretion of CXCL12/CXCR4 chemokines by CAFs, where CXCL12 promotes cancer malignancy by increasing tumor cell proliferation, migration, and angiogenesis." (PMID 35345849, 2022). "In contrast to the controls, the protein expressions of CXCR4, CXCL12, CCR7, CCL21, P-ERK1/2, MMP-9, and MMP-2 in SK-Hep1 cells were significantly increased after transfection of tumor-derived DNA, while the increase was reversed by sinobine hydrochloride." (PMID 35860597, 2022). "CXCR4-modified CAR-NK cells also significantly improved survival and tumor regression of mice bearing glioblastoma." (PMID 35432319, 2022). "In another study, the same team showed that miR-126 negatively regulates CXCR4 through the AKT and ERK1/2 signaling pathways, and thus this miR functions as a tumor suppressor in CRC cells." (PMID 35406582, 2022). "The A/NSCLC patients, one with 38.4% EGFR+ and 45.3% CXCR4+ serum sEVs and the other with 23% EGFR+ and 61.6% CXCR4+ serum sEVs both showed high levels of EGFR and CXCR4 in the primary tumor biopsy." (PMID 35269297, 2022). "When comparing results from the TMA and the whole-block tumour samples for MTC, generally higher SST and CXCR4 expression rates were observed with the whole blocks." (PMID 35799158, 2022). "CXCR4 siRNA and CCR7 siRNA attenuated tumor-derived DNA activation of ERK1/2/MMP2/9 signaling pathways in HCC cells." (PMID 35860597, 2022).
tumor (continued). "The CXCL12/CXCR4 axis can also induce vascular endothelial growth factor (VEGF) expression through the JAK2/STAT3 pathway, inducing tumor angiogenesis." (PMID 35893797, 2022). "At the same time, TAN-N2 presents an anti-inflammatory profile, exhibiting higher levels of CD184 (CXCR4), arginase-1, CCL2, CCL5, VEGF, IL-8, and MMP-9, supporting tumor growth, invasion, and metastasis." (PMID 35741003, 2022). "Stromal cell-derived factor-1 (SDF1) is highly enriched in the bone marrow for C-X-C motif chemokine receptor 4 (CXCR4)-positive hematopoietic stem cell (HSC) homing and tumor bone metastasis." (PMID 35757437, 2022). "Our findings suggest that in certain BC subtypes, a relevant cooperation between CXCR4/ACKR3 and growth factor receptors takes place to integrate concurrent signals emanating from the tumor microenvironment and foster cancer progression." (PMID 36233192, 2022). "In summary pCXCR4 tumor expression showed a significant correlation with CXCR4 tumor expression (rho = 0.699; p < 0.001) and OX40 tumor expression (rho = 0.333; p = 0.041)." (PMID 35397601, 2022). "We designated this process as “ImmunoGenic Surrender” (IGS), whereby engagement of CXCR4 induces co-internalization and surface depletion of CD47 in tumor cells, followed by phagocytosis by macrophages." (PMID 36293358, 2022). "CXCR4, a GPCR, is overexpressed in cancer cells which mediates cell proliferation, tumor growth, metastasis and tumor relapse." (PMID 35638450, 2022). "Although CXCL12, a ligand for CXCR4, acts as a tumor promoter or tumor suppressor, impairment of the CXCL12‐CXCR4 signaling axis suppresses CRC liver metastasis." (PMID 35791509, 2022). "CXCL12, produced by FAP+CAFs in the TME binds to its receptor CXCR4, expressed by T cells, thereby trapping TIL in the tumour stroma and restricting their access to tumour areas containing cancer cells." (PMID 35479076, 2022). "In turn, regulatory DCs, such as follicular DCs, maintained tumor growth and chemoresistance through the (C-X-C motif) ligand 12/chemokine (C-X-C motif) receptor 4 (CXCL12/CXCR4) axis." (PMID 36613838, 2022). "In experimental murine models, co-treatment with CXCR4 and VEGF inhibitors overcomes this bypass, exerting a synergistic effect on limiting tumor growth." (PMID 36568151, 2022). "CXCR4 and SDF-1α have been reported to act as positive regulators of tumor cell metastasis in solid tumors." (PMID 33918655, 2021). "Fu and colleagues constructed a multifunctional NP (MnIOMCP) for positive tumor-targeting T1-weighted and T2-weighted (T1−T2) dual-modal MRI-guided bio-PTT through bioconjugation of the CXCR4 antagonist monocyclic peptides (MCP) with MnIO NPs." (PMID 34072160, 2021). "In the bone marrow and spleen of 4T07 tumor‐bearing mice, CD11b+ Ly6G+ CD205+ cells also expressed high levels of CXCR4." (PMID 34646521, 2021). "Antagonists of CXCR2 (S-265610) and CXCR4 (AMD3100) altered the recruitment of immature myeloid cells (iMCs) to the tumor and thus reverted the environment that favors tumor progression." (PMID 33968014, 2021). "In the ectopic tumour model receiving castration and bicalutamide therapy, massive solid tumours were observed in ALDH+CD44+CXCR4+CD24+-cell-injected mice, whereas the ALDH−CD44−CXCR4−CD24− cells yielded smaller tumours." (PMID 34247196, 2021). "Treatment of orthotopic HT-29 xenografts with conventional chemotherapeutic agents resulted in a decrease in CXCR4 and increase in CD26 tumor expression, which abrogated chemotaxis towards CXCL12." (PMID 34503058, 2021). "In addition, cancer cell migration involving the CXCL12→CXCR4 axis may be caused by other cells—for example, CAFs in gastric cancer, where chronic hypoxia increases the expression of CXCL12 and thus acts on tumor cells with a hypoxia-enhanced expression of CXCR4." (PMID 33467722, 2021).
tumor (continued). "Bone resorption promoted by tumor cells (secretion of PTHrP, IL-11, CTGF, CXCR4, MMP-1) releases factors that stimulate tumor cells themselves, establishing a positive feedback mechanism (vicious cycle) that results in the spread of bone metastatic disease." (PMID 34212564, 2021). "A role of CXCR4 in antitumor responses is unexpected, since the CXCL12‐CXCR4 axis has been so far correlated with tumor initiation and progression." (PMID 33956406, 2021). "By preventing CXCL12/CXCR4 crosstalk, exposure to plerixafor resulted in reduced ERK1/2 signaling and consequently, decreased proliferation and invasion of disseminated tumor cells." (PMID 34831167, 2021). "Recent preclinical studies have shown that DPP-4i can increase viability and proliferation of tumor cells, and accelerates EMT through the CXCL12/CXCR4/mTOR axis both in vitro and in vivo." (PMID 36860286, 2021). "In a murine PDAC model, it was shown that CAFs prevent CD8+ T cells from reaching the tumor cells, a mechanism mediated by production of CXCL12 that retains CD8+ T cells in the stroma via CXCR4 ligation." (PMID 34203869, 2021). "Malignant cells express high levels of CXCR4, and metastasis target organs express high levels of SDF-1, allowing tumor cells to migrate to target organs via SDF-1/CXCR4 pathway chemotaxis." (PMID 33906294, 2021). "Mechanistically, knockdown of CTNND1 promoted tumor cells EMT and homing to the bone via upregulation PI3K/AKT/HIF-1α/CXCR4 pathway." (PMID 34830862, 2021). "Significant increases were observed in the expressions of CXCR4, FGF-2, VEGF-A, EGFR and ERK2 (MAPK1) in the IR/Ipsi-tumor group compared to the Sham-IR/Tumor group." (PMID 34764346, 2021). "Using this method, we detected the upregulation of c-MYC and CXCR4 in both tumor and polyp, as well as downregulation of CD26 and Oct4 in tumor when comparing with normal plus polyp and polyp, respectively." (PMID 34335790, 2021). "In AML, CSCs express CXCL12 and CXCR4, with CXCL12 being a promoter of CSC survival and tumor repopulation by regulating the interaction with the stromal microenvironment." (PMID 33530455, 2021). "While the systemic tumor biodistribution of EPI-X4-based materials is modest, this peptide shows potent proapoptotic effects on CXCR4+ cancer cells." (PMID 34208189, 2021). "CXCR4, nominated from literature comention with GPRC5C, has roles in immunity and a tumor microenvironment in addition to angiogenesis." (PMID 34007962, 2021). "In tumor samples of NET Patients, a rise in CXCR4 expression and a concomitant decrease in SSTR2 expression were found with increasing degrees of malignancy." (PMID 33671498, 2021). "Nevertheless, FAP+ CAFs depletion disrupted a CAF/cancer cell dialog through CXCR4/CXCL12 pathway inhibition, thereby restoring immune control of tumor growth." (PMID 34298680, 2021). "Inhibitors of the SDF-1 receptor CXCR4, such as AMD3100 (Plerixafor), prevent SDF-1/CXCL12-mediated recruitment of bone marrow-derived precursor cells to the tumor site." (PMID 33921099, 2021). "In fibrin/ccRCC ECM cultures approximately 37% of cells are VIM+/CXCR4+ presumptive tumor cells, and 53% are VIM+/CXCR4− presumptive fibroblasts." (PMID 34884982, 2021). "Taken together, BATF2 inhibits tumour growth and MDSCs recruitment most likely through a decrease of the SDF-1α/CXCR4 signalling." (PMID 33452462, 2021). "In the case of hematopoietic tumors, CXCR4 antagonists, such as AMD3100 and AMD3465, potentiated the clinical efficacy of conventional therapies by mediating the trafficking of tumor cells from the bone marrow milieu." (PMID 34575965, 2021). "A recent study shows that overexpression of CXCR4 in CD8+ T-cells redirects them to CXCR12+ cells in the BM vascular niche and promotes their memory differentiation and anti-tumor response." (PMID 34395425, 2021). "Conversely, our results show that NANOG is a transcriptional activator of CXCR4 expression, suggesting a role for NANOG in tumor progression." (PMID 34638956, 2021).